IL17F (interleukin 17F)
Description:
Effector cytokine of innate and adaptive immune system involved in antimicrobial host defense and maintenance of tissue integrity. IL17A-IL17F signals via IL17RA-IL17RC heterodimeric receptor complex, triggering homotypic interaction of IL17RA and IL17RC chains with TRAF3IP2 adapter through SEFIR domains. This leads to downstream TRAF6-mediated activation of NF-kappa-B and MAPkinase pathways ultimately resulting in transcriptional activation of cytokines, chemokines, antimicrobial peptides and matrix metalloproteinases, with potential strong immune inflammation. IL17A-IL17F is primarily involved in host defense against extracellular bacteria and fungi by inducing neutrophilic inflammation (By similarity). As signature effector cytokine of T-helper 17 cells (Th17), primarily induces neutrophil activation and recruitment at infection and inflammatory sites (By similarity). Stimulates the production of antimicrobial beta-defensins DEFB1, DEFB103A, and DEFB104A by mucosal epithelial cells, limiting the entry of microbes through the epithelial barriers (By similarity). IL17F homodimer can signal via IL17RC homodimeric receptor complex, triggering downstream activation of TRAF6 and NF-kappa-B signaling pathway. Via IL17RC induces transcriptional activation of IL33, a potent cytokine that stimulates group 2 innate lymphoid cells and adaptive T-helper 2 cells involved in pulmonary allergic response to fungi. Likely via IL17RC, promotes sympathetic innervation of peripheral organs by coordinating the communication between gamma-delta T cells and parenchymal cells. Stimulates sympathetic innervation of thermogenic adipose tissue by driving TGFB1 expression (By similarity). Regulates the composition of intestinal microbiota and immune tolerance by inducing antimicrobial proteins that specifically control the growth of commensal Firmicutes and Bacteroidetes (By similarity).
Synonyms: IL-17F; ML-1; ML1; CANDF6
Tractability: Small molecule: a structure with a bound ligand is known. Antibody: an approved drug acts on it; its Gene Ontology location is reachable by antibodies, with high confidence; UniProt places it where antibodies can reach, with medium confidence; UniProt predicts a signal peptide or a membrane-spanning region. Other modalities: a drug acting on it is in phase 2 or 3 trials.
Target class: Secreted protein
Gene: Protein-coding gene on chromosome 6 (52,236,681 to 52,245,689, reverse strand). Ensembl gene ENSG00000112116.
Subcellular location: Secreted
Pathways (Reactome):
Immune System: Interleukin-17 signaling; Interleukin-4 and Interleukin-13 signaling
Disease: SARS-CoV-2 activates/modulates innate and adaptive immune responses
Gene Ontology:
Molecular function: cytokine activity; cytokine binding; protein binding; protein homodimerization activity; cytokine receptor binding; protein heterodimerization activity
Biological process: cartilage development; interleukin-17-mediated signaling pathway; negative regulation of angiogenesis; positive regulation of chemokine (C-X-C motif) ligand 1 production; positive regulation of cytokine production; positive regulation of interleukin-6 production; positive regulation of lymphotoxin A production; regulation of granulocyte macrophage colony-stimulating factor production; regulation of interleukin-2 production; regulation of interleukin-6 production; regulation of interleukin-8 production; regulation of transforming growth factor beta receptor signaling pathway; protein K63-linked ubiquitination; T-helper 17 type immune response; defense response to Gram-negative bacterium; defense response to Gram-positive bacterium; inflammatory response; positive regulation of antimicrobial peptide production; positive regulation of tumor necrosis factor superfamily cytokine production
Cellular component: extracellular region; plasma membrane
Genetic constraint (gnomAD): Loss-of-function variants: 10 observed, 15.28 expected, observed/expected ratio (o/e) 0.65, 90% interval 0.4 to 1.11. The upper end of that interval is the gene's LOEUF score, 1.11, which puts it in group 4 of 6, group 1 being the genes least tolerant of losing a copy. Missense variants: 202 observed, 218.28 expected, observed/expected ratio (o/e) 0.93, 90% interval 0.82 to 1.04. Synonymous variants: 94 observed, 84.94 expected, observed/expected ratio (o/e) 1.11, 90% interval 0.94 to 1.31.
Homologues: Orthologues: chimpanzee IL17F (98% identical), macaque IL17F (94% identical), guinea pig IL17F (58% identical), pig IL17F (56% identical), rat Il17f (56% identical), rabbit IL17F (56% identical), dog IL17F (55% identical), mouse Il17f (55% identical), tropical clawed frog il17f (35% identical), zebrafish il17a/f3 (25% identical), zebrafish il17a/f1 (23% identical), zebrafish si:dkey-66g10.2 (18% identical), and 1 more. Paralogues in human: IL17A (42% identical), IL17C (29% identical), IL17B (25% identical), IL17D (24% identical), IL25 (20% identical).
Diseases named in the same sentence as IL17F in open-access papers:
IL17F is named in the same sentence as 261 diseases in open-access papers, as found by Europe PMC text mining. Sharing a sentence is not in itself a finding about the gene and the disease. The quoted sentences say what the papers report.
psoriasis (186 papers, 2012 to 2026). An autoimmune condition characterized by red, well-delineated plaques with silvery scales that are usually on the extensor surfaces and scalp. "Monoclonal antibodies designed to target IL-17A, IL-17F, IL-17RA, and IL-23 have been authorized for clinical use in treating IL-17-associated autoimmune disorders, such as psoriasis." (PMID 40536951, 2026). "Its mechanism of action involves dual inhibition of interleukin (IL)-17A and IL-17F, which are implicated in IL-23-dependent and IL-23-independent psoriasis." (PMID 41551623, 2026). "In psoriasis, tapinarof reduces the levels of key pathogenic cytokines, including IL-17A, IL-17F, IL-22, and IL-23." (PMID 40162433, 2025). "The researchers evaluated the PASI 75 response in a study group of 194 psoriasis patients and associated the IL17F rs763780 TT genotype with a better response to treatment with ustekinumab." (PMID 38331704, 2024). "Interleukin-17F (IL-17F) is another member of the IL-17 cytokine family that, like IL-17A, has been implicated in the pathogenesis of psoriasis." (PMID 38541607, 2024). "Based on the information the authors obtained from the present data, we would like to underline the relationship of IL-17F with psoriasis." (PMID 38331704, 2024). "IL-17A and IL-17F levels have been linked to chronic inflammatory diseases, such as psoriasis, multiple sclerosis, systemic lupus erythematosus, rheumatoid arthritis, and juvenile idiopathic arthritis." (PMID 39931580, 2024). "As a result; based on the information the authors obtained from the present data, we would like to underline the relationship of IL-17F with psoriasis." (PMID 38331704, 2024). "Concurrently, this demonstrates that APLNs used in treating IMQ-induced mouse psoriasis can mitigate skin psoriasis in mice through the diminished levels of cytokines associated with psoriasis, including IL-17F, IL-22, and IL-17A etc." (PMID 39534602, 2024). "Based on currently available data, IL-17F and IL-17RA gene variants have significant effects on psoriasis." (PMID 37239484, 2023). "In different populations, SNPs belonging to IL-17RA or IL-17F and other pro-inflammatory cytokines have been associated with the susceptibility to develop psoriasis or psoriatic arthritis and with the response to biological treatment." (PMID 37239484, 2023). "Few studies on the rs763780 in IL-17F and rs4819554 in IL-17RA gene polymorphisms in psoriasis have been reported until now." (PMID 37239484, 2023). "Out of those, differentiated TH17 comprises the central pathogenic cell subtype of psoriasis, orchestrating the expression of IL-17A, IL-17F, and IL-22, amongst others." (PMID 37108251, 2023). "Protein levels of major pathogenic cytokines in psoriasis were significantly reduced during apremilast administration from a total of 129 patients, contrary to placebo, additionally revealing IL-17F levels as a putative predictor of PASI reduction." (PMID 37108251, 2023). "Increased concentrations of IL-17F have been reported in skin sections of psoriasis patients, and obesity is known to be a risk factor for the development of this disease." (PMID 35277002, 2022). "Reminiscent of IL‐17A, IL‐17F was also found to be associated with IκBζ‐mediated regulation of psoriasis‐associated genes in cultured human keratinocytes." (PMID 36245291, 2022). "In patients with moderate-to-severe psoriasis, treatment with apremilast was associated with significant reductions in plasma levels of interleukin (IL)-17F, IL-17A, IL-22, and TNF-α." (PMID 33178709, 2020). "Dysregulated expression of IL-17A and IL-17F is associated with chronic inflammatory diseases such as psoriasis, psoriatic arthritis, rheumatoid arthritis, ankylosing spondylitis, and asthma." (PMID 32973785, 2020). "In the present study, as well as in our previous preliminary study, we found that the IL17F rs763780 polymorphism is a risk locus for psoriasis development in Asian patients." (PMID 31831764, 2019).
psoriasis (continued). "Cytokine analyses were performed to investigate the effect of the mutant allele of the IL17F rs763780 polymorphism on serum levels of cytokine in the control and psoriasis groups." (PMID 31831764, 2019). "In a previous study, we identified a locus in the IL17F gene that is associated with psoriasis, the IL17F rs763780 (His161Arg) T/C variant." (PMID 31831764, 2019). "Our results suggest that this polymorphism is a potential risk locus for psoriasis and that it results in a direct increase in IL-17F production." (PMID 31831764, 2019). "Here, we aimed to study the association between the IL17F His161Arg polymorphism and the clinical manifestations of psoriasis and to determine its effect on serum levels of cytokine." (PMID 31831764, 2019). "We observed a significant relationship between an IL17F polymorphism and psoriasis and found that the presence of the minor allele, C, was significantly associated with an increased risk of psoriasis development ( > 2-fold)." (PMID 31831764, 2019). "Our study reveals an association between the IL17F His161Arg variant and psoriasis risk, and its effects on serum levels of cytokines in this population." (PMID 31831764, 2019). "Additional analyses were performed to investigate the clinical factors associated with the IL17F rs763780 polymorphism in psoriasis patients." (PMID 31831764, 2019). "The IL17F His161Arg polymorphism is a potential risk locus for psoriasis and that its variant possibly causes an increase in IL-17F and IL-12 production, leading to increased susceptibility to this condition." (PMID 31831764, 2019). "The IL17F rs763780 T/C polymorphism has been studied in various diseases other than psoriasis, and different results have been obtained depending on the disease." (PMID 31831764, 2019). "In this study, a significant increase in serum IL-12 levels was observed in psoriasis subjects harbouring the IL17F polymorphism." (PMID 31831764, 2019). "Within this family, IL-17A, IL-17C, and IL-17F are implicated in psoriasis pathogenesis as their expression is increased up to eightfold in psoriatic lesions." (PMID 30109481, 2018). "The topical application of Aldara in mice deficient in IL-17A, IL-17F, or IL-22 drastically reduced the severity of psoriasis." (PMID 29249871, 2017). "On the other hand, the blocking of neutrophil infiltration by an anti-IL-8 antibody underlined the importance of the IL-17F/IL-8 axis in the pathophysiology of psoriasis." (PMID 29249871, 2017). "Th17-derived IL17A and IL17F are linked to the pathogenesis of some autoimmune diseases, including multiple sclerosis, rheumatoid arthritis, psoriasis, and Grave’s disease." (PMID 28430123, 2017). "It is thus hypothesized that younger psoriasis patients may have lower IL‐17A, IL‐17A/F, or IL‐17F‐mediated immune responses, which may be more susceptible to bimekizumab treatment compared to elderly patients." (PMID 38482898, 2024). "The expression of many genes known to be associated with psoriasis, including Lce3f, Sprr2b, Krt15, S100a8, S100a9, Il17a, Il17f, Il18, Il20, Il22, and Ccl20, was downregulated in the skin of IMQ-treated Camk4−/− mice compared with those of IMQ-treated Camk4+/+ mice." (PMID 35869084, 2022). "The IL-17 cytokine family consists of six members (IL-17A, IL-17B, IL-17C, IL-17D, IL-17E and IL17F), with IL-17A and IL-17F being primarily associated with clinically relevant signaling in psoriasis, acting through the same receptor, but with varying potencies." (PMID 35883760, 2022). "Psoriasis patients harbouring the mutant allele had significantly increased serum levels of IL-17F." (PMID 31831764, 2019). "Very few studies on the IL17F rs763780 polymorphism in psoriasis have been reported to date." (PMID 31831764, 2019). "However, the IL17F rs763780 polymorphism still deserves attention and is worthy of investigation based on its association with psoriasis in multi-ethnic groups." (PMID 31831764, 2019).
psoriasis (continued). "Therefore, we suggest that the IL17F rs763780 polymorphism plays a critical role in the pathogenesis of psoriasis through its direct and indirect effects on the production of IL-17F and IL-12, respectively." (PMID 31831764, 2019). "Interestingly, in HLA-Cw6+ patients experiencing guttate psoriasis flare-ups associated with pharyngitis, the Th17-associated response is more pronounced, leading to significantly elevated levels of IL-17A, IL-17F, and IL-6, which are involved in Th17 differentiation." (PMID 40303401, 2025). "In particular, the NFkB-activating cytokines (LTA, IL-1B) are expected to synergize with IL-17A and IL-17F for the induction of many typical “IL-17 pathway” products in keratinocytes that initiate “feed forward” inflammation and help to maintain pathogenic gene expression profiles in psoriasis." (PMID 36110854, 2022). "From a mechanistic perspective, our results further support the biological rationale for dual IL-17A and IL-17F blockade in refractory psoriasis." (PMID 41590520, 2026). "Other cytokines from the IL-17 family—such as IL-17C, IL-17E, and IL-17F—are also believed to contribute to psoriasis development." (PMID 40536951, 2026). "Compared to IL-17A, IL-17F, and IL-17A/F heterodimers, IL-17B, IL 17C, IL-17D, and IL-17E are less characterized in the context of psoriasis." (PMID 40243580, 2025). "Although reverse translational immunology from clinical trials shows the involvement of both IL-17A and IL-17F in psoriasis, the situation in the skeleton is less clear." (PMID 41322402, 2025). "Although IL-17F is important in psoriasis, the rudimentary biology of IL-17F in the human enthesis remains undefined." (PMID 41322402, 2025). "Upon CD8 T cell activation, IL-17A and IL-17F were expressed at low and comparable levels in psoriasis patients and healthy controls." (PMID 40391222, 2025). "We present the first case of superimposed linear psoriasis that was resistant to several biologic agents but responded favorably to bimekizumab, a monoclonal antibody targeting both interleukin (IL)-17A and IL-17F." (PMID 40539143, 2025). "Dendritic cells and macrophages in the dermis of psoriasis produce IL-23, which induces the activation of Th17 cells and γδ T cells and the release of inflammatory cytokines, such as IL-17A, IL-17F, IL-22, IL-6 and tumor necrosis factor-α (TNF-α)." (PMID 40303403, 2025). "In psoriasis, curcumin exhibits its anti-inflammatory effects by reducing the expression of cytokines such as interleukin-17A (IL-17A), interleukin-17F (IL-17F), interleukin-22 (IL-22), IL-6, IL-1β, and TNF-α, and by inhibiting NF-κB activation." (PMID 40718452, 2025). "Bimekizumab, a monoclonal antibody that targets IL-17A and IL-17F, received marketing approval in Europe in 2021 and in Japan in 2022 for the treatment of psoriasis and PsA." (PMID 40303401, 2025). "The rationale for investigating these biomarkers stems from studies demonstrating that serum levels of TNF-α, IL-17A, IL-17F, and IL-12/23 play a critical role in the development of psoriasis clinical manifestations and response to treatment." (PMID 40699767, 2025). "IL-17F is known to contribute to the onset of psoriasis, while other IL-17 family members show a weaker link to disease progression, necessitating further exploration." (PMID 40303401, 2025). "According to clinical trials, the dual neutralization of IL-17A and IL-17F provides a more prominent suppression of inflammation, resulting in a more significant improvement in clinical outcomes in psoriasis than IL-17A inhibitors." (PMID 40277935, 2025). "A new therapeutic antibody, bimekizumab, which blocks both IL-17A and IL-17F, is approved for the treatment of severe psoriasis and currently being tested for its effect on HS." (PMID 41142785, 2025). "Blocking the IL-17F pathway has emerged as a promising therapeutic strategy in psoriasis management." (PMID 38541607, 2024).